APOL1 (apolipoprotein L1)
Diseases named in the same sentence as APOL1 in open-access papers (continued):
Sharing a sentence is not in itself a finding about the gene and the disease.
kidney disease (continued). "These new anti-APOL1 therapeutics represent a long-needed advance for kidney diseases that have previously lacked any specific therapeutics and disproportionally impact underserved populations." (PMID 40940784, 2025). "The list of kidney diseases has been expanded and is now under the rubric of a new class designated APOL1 mediated kidney disease (AMKD), and even extends to non-kidney phenotypes." (PMID 40643530, 2025). "In fact, APOL1 variants are known to contribute to faster progression to ESRD in African Americans, regardless of the underlying kidney disease." (PMID 39457385, 2024). "To date, there is no definitive evidence that the course of APOL1-mediated kidney disease is ameliorated by any particular regimen in CKD presentations." (PMID 39056771, 2024). "Less attention has been paid to circulating plasma APOL1 protein, which may be due to several studies that associate kidney allograft failure to donor genotype and to a study showing that plasma levels of risk-variant APOL1 did not associate with renal disease." (PMID 36279295, 2022). "Not only FSGS, these APOL1 risk variants much increase rates of hypertension-associated ESRD, HIV-associated nephropathy, end-stage of lupus nephritis, and other forms of non-diabetic kidney diseases." (PMID 35408886, 2022). "Most individuals carrying two APOL1 RVs do not develop kidney disease; this suggests that additional cellular stressors such as inflammation are required to upregulate APOL1 and induce podocyte injury." (PMID 34440683, 2021). "In an analysis of 10,605 black participants without renal disease from the REGARDS Study, possession of two APOL1 high-risk variants significantly increased the risk for ischemic and small vessel disease-related stroke." (PMID 34828431, 2021). "Mouse models are the most frequently used animal models and have been widely explored to investigate APOL1 kidney disease, even though mice do not have an ortholog to the human APOL1 gene." (PMID 34765626, 2021). "Recent work has examined the effect of APOL1 genotype on BP in young AAs without diagnosed kidney disease, but has yielded mixed results." (PMID 31532792, 2019). "Together with our previous data showing no cytotoxicity of overexpressed APOL1 isoform lacking exon 4, we propose that morpholino-induced APOL1 isoform switch may provide a new tool to identify in vivo molecular mechanism(s) by which risk alleles promote or mediate the kidney disease phenotype." (PMID 29880816, 2018). "Finally, the indications for APOL1 genotyping in our patients do not reflect the severity of kidney disease, because all patients of African origin are genotyped." (PMID 38899219, 2024). "To test the hypothesis that the G2-p.N264K haplotype differs in its genetic impact from the more common G2 risk allele without the p.N264K variant, we sought to compare its frequency in APOL1-HR subjects with FSGS to APOL1-HR controls without kidney disease." (PMID 38036523, 2023). "In addition, observations here indirectly support conclusions from prior studies that circulating APOL1 protein is unlikely to contribute to kidney disease pathogenesis as it is not the source of kidney-localized APOL1." (PMID 34138902, 2021). "Taken together, these data indicate that human APOL1 G2/G2 podocyte model can mirror in vitro the renal cytopathology observed in patients carrying APOL1 HRG, representing a novel tool to support the investigation of APOL1-related kidney diseases and to test new therapies." (PMID 34440683, 2021). "However, if low nephron endowment does contribute to insidious APOL1 kidney disease, then these clinical trials may have some non-responders." (PMID 40940784, 2025).
infection (56 papers, 2009 to 2026). The state of being infected such as from the introduction of a foreign agent such as serum, vaccine, antigenic substance or organism. "The primary cohort included 2242 Black patients hospitalized with an infection; 361 (16.1%) patients carried a high-risk APOL1 genotype and 1881 (83.9%) carried low-risk genotypes." (PMID 37882666, 2023). "We present a case of an 18-year-old male with CG associated with PB19 infection who was heterozygous for APOL1 G1 and G2 genetic variants." (PMID 32566445, 2020). "Studies in the Democratic Republic of Congo (DRC), Cameroon, Cote D’Ivoire, Guinea and Uganda have found evidence for polymorphisms in HP, IL6 and APOL1 associated with outcome of infection." (PMID 29470556, 2018). "The APOL1 G2 allele carriers had a higher risk of developing HAT after infection by T. b. gambiense than the APOL1 G0 individuals (p = 0.0011, OR = 2.70, CI95 = [1.49–4.91], BONF = 0.0301)." (PMID 28827791, 2017). "rhodesiense STIB900 genome contained the SRA gene (serum resistance-associated; Tb927.9.17380), whose product neutralizes ApoL1, the trypanolytic factor of human serum that protects humans from infection by T. b." (PMID 26973180, 2016). "In vivo, specific podocyte cytotoxicity of the APOL1 risk variants was linked to the strong induction of APOL1 expression occurring during infection-induced inflammation, particularly with viruses, and it was ascribed to the circulating isoform of the APOL1 variants." (PMID 39451256, 2024). "This may facilitate observations of key pathogenic events associated with infection, immune responses, and APOL1 gene expression." (PMID 37927001, 2023). "Eight of 13 CG biopsy samples obtained from the first half of 2016 from a large Brazilian kidney biopsy center were positive for arbovirus, wherein six samples were positive for dengue, one for Zika, and one for a concomitant infection; only one case had APOL1 mutations." (PMID 35308512, 2022). "Therefore, the presence of one of the APOL1 variants G1 or G2 appears to protect against infection of several subspecies of Trypanosoma brucei." (PMID 35095882, 2021). "Last, we assessed the association of APOL1 on multiple OI infections (or co-infections)." (PMID 33674766, 2021). "The seven-fold reduced susceptibility for individuals with APOL1 G2 variant is consistent with the in vitro evidence of lysis of T. b. rhodesiense by plasma containing the APOL1 G2 allele and a study that showed that mice with APOL1 G2 survived longer after infection with T. b. rhodesiense." (PMID 31412021, 2019). "Indeed, a frameshift mutation, found in both ApoL1 alleles of the patient, resulted in the ability of trypanosomes to establish infection and to survive in the human bloodstream." (PMID 30333827, 2018). "The association between APOL1 variants and infection outcome for T.b." (PMID 28537557, 2017). "In addition, a protective effect has been observed in vitro and in vivo of the G2 allele of APOL1 against infections due to T. b. rhodesiense." (PMID 29077717, 2017). "RhIL-1β increases expression of DC-SIGN also in CIHPs stably transfected with either WT or G1/G2 APOL1 Vs, therefore, we used this experimental model to test the direct impact of rhIL-1β priming on HIV-1 entry and trans-infection to CD4pos T lymphocytes in the context of APOL1 polymorphism." (PMID 27599995, 2016). "The higher amounts of virus in CIHPs transfected with the G1 or the G2 APOL1 Vs also induced a significant higher trans-infection of co-cultured CD4pos T cells that showed a significant increase of viral replication compared to that exerted by CIHPs transfected with WT APOL1 allele." (PMID 27599995, 2016). "Indeed, APOL1 expression is induced by inflammatory cytokines such as tumor necrosis factor alpha and gamma-interferon; thus increased transcription of the gain-of-function variant APOL1 is most likely to occur in the setting of severe infection." (PMID 37882666, 2023).
infection (continued). "Hence, it seems that the human immune system might have found unique ways of dealing with trypanosomosis both in terms of dealing with parasite killing through the TLF1/2 ApoL1 mechanisms, as well as the control of infection-associated anemia." (PMID 30333827, 2018). "Some primates are immune to infection by most African trypanosome parasites due to apolipoprotein L-1 (APOL1), a primate-specific ion channel-forming protein." (PMID 41894328, 2026). "Specifically, human APOL1 and APOL3 appear to control membrane remodeling linked to pathogen infection." (PMID 39768205, 2024). "Despite their differential activities, APOL1 and APOL3 share strongly increased expression under inflammatory conditions associated with resistance to infection." (PMID 38478101, 2024). "Apolipoprotein-L1 (APOL1) is a membrane-interacting protein induced by inflammation, which confers human resistance to infection by African trypanosomes." (PMID 39451256, 2024). "In contrast, APOL1-G1, has reduced binding to APOL1 compared to that of APOL1-G0, and appeared later in response to infections with T. brucei gambiense, which also evolved other mechanisms to block the trypanosomal effects of APOL1-G0." (PMID 37969018, 2023). "APOL1 improves gene function and fights against infections through G1 (missense) and G2 (deletion of two amino acids) mutations." (PMID 35308512, 2022). "This indicates that when “natural resistance” such as the resistance conferred by ApoL1 fails, the antibody-mediated immune response does provide a second defense barrier against the progressing of infection." (PMID 30333827, 2018). "Humans are naturally resistant to infection by most African trypanosomes species because of a lytic protein component in their blood, called APOL1." (PMID 27494254, 2016). "Humans are protected against infection from most African trypanosomes by lipoprotein complexes present in serum that contain the trypanolytic pore-forming protein, Apolipoprotein L1 (APOL1)." (PMID 27494254, 2016). "Podocytes transfected with APOL1 WT and pre-treated with rhIL-1β also resulted with the significant upper trans-infection of CD4pos T lymphocytes after 5 days of co-culture." (PMID 27599995, 2016). "Humans resist infection by the African parasite Trypanosoma brucei owing to the trypanolytic activity of the serum apolipoprotein L1 (APOL1)." (PMID 26307671, 2015). "The wild-type, or G0, form of APOL1 provides humans with protection against infection by the parental African trypanosome species, trypanosoma brucei brucei." (PMID 25933006, 2015). "ApoL1 restricted infection of cells by the AR86 strain of Sindbis virus and more modestly by Venezuelan equine encephalitis virus and human parainfluenza virus type 3, but increased infection by Yellow fever virus." (PMID 26196674, 2015). "This differential infection ability results from the presence in normal human serum (NHS) of the trypanolytic factor apolipoprotein L1 (APOL1), which kills T. b." (PMID 26307671, 2015). "Although both WT and delTKIQ apoL1 almost completely erased the first peak of infection by ETat 1.2S parasites, infection reappeared afterwards and in both cases all mice died between days 12 and 15 post-inoculation (data not shown)." (PMID 19997494, 2009). "Whereas neutralizing surface-exposed APOL1 with specific APOL1-targeting proteins or drugs appears to reduce the disease, totally inactivating APOL1 is expected to increase the patient’s sensitivity to pathogen infection." (PMID 39768205, 2024). "Analysis of COVAN samples may be useful in determining the initiating events in an APOL1-dependent FSGS because there is a short time frame from infection and symptom onset to the development of proteinuria and biopsy." (PMID 37927001, 2023).
infection (continued). "The proteins altered during the infection and maintained altered also after recovery enriched functions related to cholesterol transport and metabolism, including APOL1, APOA2, and SERPINA12 for moderate patients, and APOA5, APOL1, APOA2, and CSE1 for severe ones." (PMID 35269564, 2022). "Thus, APOL1 initially allowed humans to survive infection by T. b." (PMID 38478101, 2024). "However, a recent report of infection in a patient with no previous immunological risk, 2 wild-type APOL1 alleles and a normal serum APOL1 concentration suggested that T. evansi is a true zoonosis with a risk of infection for the general population." (PMID 31881926, 2019). "We also detected enhanced transcription of the apolipoproteins APOL1, APOL3, and APOL4, which also act as immune regulators in response to infection." (PMID 41416938, 2025). "Among these transcripts we identified the apolipoprotein L gene family including, APOL1, APOL2 and APOL6 with up to a fivefold increase of expression (q value ≤ 0.05) after infection with ZIKV." (PMID 39885287, 2025). "In conclusion, through their key involvement in mitophagy and apoptosis, APOL1 and APOL3 contribute to avoiding the detrimental effects of infection-induced inflammation on mitochondrial function." (PMID 39768205, 2024). "These mice produce detectable levels of the TLF proteins (APOL1 and HPR) for at least 3 days post infection (Day 2- peak time of TLF production)." (PMID 34559857, 2021). "Thus, APOL1 and APOL3 are involved in distinct activities controlling membrane dynamics in response to pathogen infection and, consequently, innate immunity induction." (PMID 39768205, 2024). "APOL1 and CMPK2 are mainly induced by interferon and proinflammatory cytokines, and LGALS9 is widely expressed in cells and immune system tissues and plays a major role in the inflammatory response and immune response against infection." (PMID 37112994, 2023). "Interestingly, HDLs also play a role in fighting infection parasites, and a specific component of HDL, the apolipoprotein L-1 (apoL-1), confers innate immunity against Trypanosoma cruzi by favoring the lysosomal swelling that kills the parasite." (PMID 36651718, 2023). "In addition, at least three studies have shown expression of APOL1 and APOL6 genes change in response to infection by the intracellular bacterial pathogens Mycobacterium and Listeria." (PMID 34252458, 2021). "Nevertheless, a lack of the trypanolytic ApoL1 protein could be responsible for human infection with animal trypanosomes, as already described for one T. evansi infection in India and one transient T. b brucei infection in Ghana." (PMID 30125276, 2018). "For P. hamadryas, serum and APOL1 have not yet been tested against T. b. gambiense, however a laboratory infection of two individual baboons with a strain of T. b. gambiense group 1 suggested hamadryas baboons to display a level of trypanotolerance to infection." (PMID 27494254, 2016). "Next to the direct effect of the virus to the podocytes, which has not been shown for these infections, systemic immune response, similar to the response to HIV or SARS-CoV2, might be responsible for upregulation of APOL1 or could directly influence podocyte function." (PMID 35095882, 2021).
tumor (28 papers, 2009 to 2025). "Correlation analysis indicated significant associations between APOL1 expression and variables, including pathologic N stage, overall pathologic stage, age, histological type, primary neoplasm focuses type and neoplasm location (P<0.05)." (PMID 41378287, 2025). "In ccRCC, apolipoprotein L1 (APOL1) is transcriptionally upregulated in a distinct metastatic tumor cell cluster and is associated with poor survival." (PMID 38680858, 2024). "The protective gene (APOL1) was downregulated, while the other four risk genes were upregulated in tumor, compared with the adjacent normal tissue, which were consistent with the RNA-seq data above." (PMID 35140317, 2022). "Furthermore, APOL1, TNF, and VIM are co-expressed in myeloid cells, while APOL1 and TNF are also co-expressed in T cells and NK cells, indicating the association between APOL1 and the lactylation–PANoptosis axis in regulating tumor progression." (PMID 40649778, 2025). "Using RNA-seq data from TCGA and GTEX, APOL1 expression was analyzed in various tumor tissues compared to the respective normal tissues." (PMID 41378287, 2025). "The expression of APOL1 gene inhibited tumor formation, proliferation, metastasis and xenograft tumor formation." (PMID 40491925, 2025). "In the present study, it was shown that APOL1 functioned as a tumor suppressor in THCA, whereas previous studies have identified APOL1 as an oncogene that promotes proliferation and inhibits apoptosis through the NOTCH1 signaling pathway." (PMID 41378287, 2025). "In summary, APOL1 not only promotes tumor cell proliferation but also likely participates in inhibiting tumor cell immune evasion in LUAD." (PMID 40649778, 2025). "To assess the role of APOL1 in tumor progression, we generated a stable knockdown of APOL1 in the primary cancer A-498 and 786-O cells and overexpressed APOL1 in the metastatic Caki-1 cells by lentiviral transfection." (PMID 38680858, 2024). "Altogether, APOL1 is an upstream regulator of these signaling pathways which ultimately leads to ccRCC tumor progression." (PMID 38680858, 2024). "Based on the experimental data, in ccRCC, the HIF-2α/LINC02609/APOL1 axis can regulate the expression of APOL1, thus interfering with lipid storage, promoting endoplasmic reticulum homeostasis and regulating tumor progression in ccRCC." (PMID 38263248, 2024). "HIF2α dependent APOL1 accelerates tumor growth in ccRCC cells through promoting lipid deposition and tumor progression." (PMID 38263248, 2024). "Our discovery revealed the connection between miR-30a-3p and APOL1 as the miRNA to be the inhibitor of the tumor suppressor." (PMID 38680858, 2024). "As a result, APOL1 was highly expressed in tumors of primary cancer cells and lowly expressed in tumor of metastatic cells." (PMID 38680858, 2024). "In in vivo model, the expression of miR-30a-3p was low in tumors of primary cancer cells and high in tumor of metastatic cells, which negatively correlated with APOL1 expression." (PMID 38680858, 2024). "We analyzed APOL1 expression in 150 ccRCC samples by immunohistochemistry and found that high APOL1 protein expression was significantly correlated with the tumor (T) and stage." (PMID 38263248, 2024). "APOL1, 2, 3, and 6 were differentially expressed in tumor and non-tumor tissues in the GSE14520 cohort." (PMID 38017264, 2023). "Similar to ApoE2, ApoL1 is also up-regulated in PC tissues and it acts as an oncogene to induce proliferation and prevent apoptosis of the tumor cells via stimulating the Notch1 signaling pathway." (PMID 36506554, 2022). "The most striking effect of the APOL1 RV effect was demonstrated in vivo by the complete abolishment of tumor growth in immunodeficient mice." (PMID 35159001, 2022). "Tumour suppressor genes expression levels (APOL1, TP53INP1 and ZC3H12A) were low in BLCA tissues comparing with normal bladder." (PMID 33960661, 2021).